C4B (complement C4B (Chido/Rodgers blood group))
Diseases named in the same sentence as C4B in open-access papers (continued):
Sharing a sentence is not in itself a finding about the gene and the disease.
Alzheimer disease (9 papers, 2019 to 2025). A progressive, neurodegenerative disease characterized by loss of function and death of nerve cells in several areas of the brain leading to loss of cognitive function such as memory and language. "Remarkably, we found that this cluster shared some signatures with MOL2, while Alzheimer’s disease risk factors such as C4b, Apoe and Cd742,27,28 are strongly expressed (and Source data file)." (PMID 36781874, 2023). "In humans, C4B has been implicated in Alzheimer’s disease, indicating that C4B might be involved in brain degeneration." (PMID 40217412, 2024). "Starting at month-6, this upregulated protein set includes neuroinflammatory-related proteins like complement C4-B, glial fibrillary acidic protein, protein-arginine deiminase type-2, vimentin, and vitronectin that have long been associated with Alzheimer’s disease." (PMID 35944844, 2022). "While previous research has shown that Apoe and C4b are co-expressed in complement pathways within Alzheimer’s disease–specific co-expression networks, our findings extend this knowledge by providing spatial context to their co-expression dynamics over time." (PMID 41370198, 2025). "CR1 is a top Alzheimer’s disease gene that plays a critical role in the complement cascade as a receptor for the C3b and C4b complement components, and potentially helps clear amyloid-beta (Aβ)." (PMID 31104630, 2019). "Among the top targets identified from druggability analysis, four of them (i.e., DRD2, C4B, GABA-A-R, C5AR1) were shown in the single-nuclei sequencing data because of their clinical relevance to inflammation involved in Alzheimer’s disease." (PMID 39897171, 2024). "In the brain, Alzheimer’s disease and memory-related genes (Camk2n1, Apod, and Serpina3n), and immune-response-related genes (Spp1, CD68, GFAP, Mpeg, Ddx3y, Lyz2, CTSZ, Tyrobp, C4b, and C1qa), were selected for mRNA qPCR analysis in adenine-induced CKD mice." (PMID 35447931, 2022). "Six genes C4A, C4B, CXCL12, FCGR3A, IL1B, and MMP3 were identified as the most significant crosstalk genes linking chronic periodontitis and Alzheimer's disease." (PMID 33869630, 2021).
autism (8 papers, 2008 to 2020). Persistent deficits in social interaction and communication and interaction as well as a markedly restricted repertoire of activity and interest as well as repetitive patterns of behavior. "The deficiency of C4B in the blood correlates with the complement C4B gene null allele being more frequent in individuals with autism." (PMID 28031921, 2015). "This extended haplotype also contains two genetic loci previously shown to be associated with autism, the C4B null allele, and HLA-DR4." (PMID 24672722, 2014). "After this observation, it was also noted that subjects with autism had a significant deficiency in the plasma C4B protein." (PMID 22928105, 2012). "It was reported 20 years ago that subjects with autism had a significant increase in the C4B null allele (C4B gene deletion) compared to control subjects." (PMID 22928105, 2012). "Strong associations also appear in the class III region where the C4B null allele has been associated with autism with relative risks of 4.3 and 4.6, and an odds ratio of 6.3." (PMID 22928105, 2012). "Although the combined autism and control study subjects had 50 C4B null alleles only 15 CYP21A2 mutations were detected in over 2250 genotypes." (PMID 18179706, 2008). "Several studies have shown that the frequency of C4B null alleles is increased in individuals with autism, the most recent of which found that 42.4% of autistic subjects carry a C4B null allele compared to 14.5% of controls." (PMID 18179706, 2008). "In addition, several studies have noted an association of autism with the C4B null allele in the class III region, with relative risks of 4.6 and 4.3." (PMID 33384710, 2020). "The link of C4B null allele to autism and to a family history of autoimmunity is described." (PMID 28031921, 2015). "Also, there is a strong association between autism and the major histocompatibility complex for the null allele of C4B in class III region." (PMID 21513576, 2011). "Therefore, the aim of the present research was to determine if the C4B null allele, found frequently in subjects with autism, is associated with CYP21A2 mutations." (PMID 18179706, 2008). "These initial findings of an increase in the deletion of the C4B gene was supported by examining a new population of subjects with autism." (PMID 22928105, 2012). "Despite of the fact that the origins of autoimmunity and the induction of the production of brain auto-antibodies in autism are unknown, the major histocompatibility complex genes and their products (e.g., HLA-DRB1 and C4B null alleles) might be involved." (PMID 21696608, 2011). "Samples from subjects diagnosed with autism and non-autistic controls (controls) previously typed for C4B null alleles were studied." (PMID 18179706, 2008). "However, three studies indicate that the complement C4B gene null allele (i.e. the missing or nonfunctional C4B gene) is significantly more frequent in individuals with autism." (PMID 18179706, 2008).
viral infection (8 papers, 2018 to 2024). "Interestingly, we also found a strong increase in expression of the complement component C4b, which has previously been observed in the contexts of viral infection and ageing, in microglia that also concurrently express a strong type 1 interferon signature." (PMID 33183319, 2020). "We failed to generate any C4b variant viruses that could escape M1-1 and M1-12; this may be due to the fact that these antibodies partially neutralize and are unable to fully prevent virus infection even at the highest concentration tested." (PMID 37262073, 2023). "Besides, we also found several instances including differentially expressed C4B gene and SMAD3/SMAD4/JUN/FOX complex to explore potential possible mechanistic details of how non-tumor individuals who are not susceptible fend off viral infections." (PMID 38752789, 2024). "For example, the NS1 glycoprotein of some Flaviviruses (i.e. Dengue, West Nile and Yellow fever), which is expressed on the surface of and secreted by infected cells, can suppress complement by recruiting and activating C1s and C4BP to promote cleavage of C4 and inactivate C4B." (PMID 30774579, 2019).
diabetes (7 papers, 2008 to 2025). "In conclusion, our study provides transcriptomic data of an animal model with progressive diabetes-induced nephrotoxicity, and also demonstrates that C4b, CXCR6, CFD, and LIF are specific and sensitive biomarkers for early detection of diabetic nephropathy." (PMID 33922243, 2021). "Using proteomic research methods, 2D electrophoresis and mass spectrometric analysis, increased concentrations of the complement system sub-components C1r, C3 and C4-B, α-1-antitrypsin and vitronectin were detected in patients with type 2 diabetes mellitus compared to the control group." (PMID 34948066, 2021). "Both human and animal studies determined that plasma levels of C3, C4, C4b, iC3b, MBL, MASP-2, C5b-9 Factor B, and Bb were found to be significantly increased in diabetes condition and have a role in exacerbating the pathophysiology of diabetes mellitus." (PMID 38564496, 2024). "We identified C4b, CFD, CXCR6, and LIF that were time dependently increased as diabetes progression as non-invasive biomarker candidates for diabetic nephropathy." (PMID 33922243, 2021).
Autoimmunity (6 papers, 2011 to 2023). The occurrence of an immune reaction against the organism's own cells or tissues. "Indeed, the strongest associations detected within the MHC in ASD, for the null allele of complement C4B locus, the extended haplotype B44–S30–DR4 and the third hypervariable region of HLA–DR1, are known to be predisposed to the development of autoimmunity." (PMID 36979694, 2023). "Activated C4A and C4B tend to interact or interfere with each other in moderating and propagating the activation of complement pathways, and in the fine-tuning of immunologic functions such as the induction of tolerance or suppression of autoimmunity." (PMID 34764957, 2021).
type 1 diabetes (6 papers, 2006 to 2026). "Samples from patients with type 1 diabetes (TD) had multiple C4B variants that migrated between A3 and B1 (lanes 2-7)." (PMID 34764957, 2021).
acute myocardial infarction (5 papers, 2006 to 2023). Necrosis of the myocardium, as a result of interruption of the blood supply to the area. "In fact, low C4b copy number carrier status has been reported in patients with acute myocardial infarction and stroke." (PMID 25379033, 2014). "Low expression of C4B was culpable for pathogenesis of myocardial infarction, but decrease expression of this gene may be involved in progression of CAD." (PMID 31881747, 2019).
atherosclerosis (5 papers, 2018 to 2026). A disease characterized by the build-up of fatty material and calcium deposition in the arterial wall resulting in partial or complete occlusion of the arterial lumen. "However, the reported disease associations of genetic C4B deficiency (homozygous and heterozygous deficiency combined) include also common and complex diseases such as psychiatric disorders and atherosclerosis." (PMID 29928053, 2018). "Meanwhile, C4b was also upregulated in CKD, atherosclerosis, and hypertension." (PMID 38898508, 2024).
breast carcinoma (5 papers, 2007 to 2024). "Meanwhile, complement C4-B and Crk-like protein, which are involved in the immune system, were highly expressed in breast cancer, but differences between IDC and ILC are not well characterized." (PMID 37064116, 2023).
lung carcinoma (5 papers, 2014 to 2024). "The present study also indicated that the relative mechanisms of SLC34A2 in A549 lung cancer may be associated with the activation of the complement alternative pathway (C3 and C4b) and upregulation of the expression of SELENBP1, TXNIP, PDZK1IP1 and DUSP6." (PMID 25017204, 2014). "In previous studies we found a significant elevation of proteolytic fragments of complement C4 in biological fluids from lung cancer patients using a commercial ELISA based on the detection of C4d-containing fragments (C4b, iC4b and C4d)." (PMID 29464077, 2018).
malaria (5 papers, 2005 to 2016). Malaria is a serious and sometimes fatal disease caused by a parasite that commonly infects a certain type of mosquito which feeds on humans. "Five individuals were found to have the C4B null alleles and four of these were in the uncomplicated malaria group, thus uncoupling this genetic factor from the low C levels." (PMID 19134190, 2009). "It was observed that the levels of Complement C3 and Complement C4-B, Complement C5, Complement C9, Complement factor B and Complement C1q subcomponent subunit C were significantly elevated in malaria plasma MPs compared to controls." (PMID 28352210, 2016). "Increased generation of C4b and C3b would thus assist adherence and rosetting of malaria infected parasites in the placenta." (PMID 22380611, 2012). "The mechanism by which the Sl2 and McCb alleles could confer protection from severe malaria is not known, since these polymorphisms are located near the C-terminus of the CR1 molecule in an area that is outside the binding sites for C3b, C4b, and PfEMP-1." (PMID 16277654, 2005).
thrombosis (5 papers, 2010 to 2023). "In another study investigating the significance of C3 and C4 in antiphospholipid syndrome, approximately, 40% lower levels of C4 (both C4A and C4B) were observed in thrombotic SLE patients with reference to thrombosis-free SLE patients." (PMID 35359932, 2022). "Among the NTS subjects who were not afflicted with thrombosis and SLE, there were higher mean GCN of C4A, which would be protective against SLE; and low GCN of C4B that would lead to lower C4B protein levels and thereby reducing the risk of thrombosis." (PMID 31134052, 2019). "When the aPL subjects were segregated and compared based on both thrombosis and SLE status, it revealed that the NTS group without thrombosis and SLE had the highest mean GCNs for total C4 and C4A (3.78 and 2.12, respectively), but the lowest C4B mean GCN (1.66)." (PMID 31134052, 2019).
cervical cancer (3 papers, 2021 to 2025). A primary or metastatic malignant neoplasm involving the cervix. "We speculate that in the early stages of cervical cancer, the secretion of sCD46 may mainly derived from the shedding of mCD46, which plays a role in promoting the inactivation of C3b and C4b in TME." (PMID 38919630, 2024).
co-infection (3 papers, 2013 to 2025). "In the caudal fin, Mc+ (1 day after co-infection with T. bryosalomne) fish showed mild immune activation with C4B upregulation, while Tb+ fish exhibited a stronger response involving IFI44, ISG15, RSAD2, and TLR7 signaling." (PMID 40943072, 2025). "In our study, C4B was significantly upregulated following M. cerebralis single and co-infection by 55.67-fold and 92.98-fold, respectively, and comparatively to a lesser extent in the gills of Mc+ co-infected fish." (PMID 40943072, 2025). "However after co-infection with all four MCMV strains, C4A and C4B were undetectable at this site." (PMID 23300458, 2013).
diabetic nephropathy (3 papers, 2021 to 2024). "Using diabetic nephropathy models, data demonstrate that urinary levels of C4b, CXCR6, CFD, and LIF were markedly increased compared with conventional biomarkers (KIM-1, NGAL)." (PMID 33922243, 2021). "Our results showed that expression levels of C4b in rat urine, kidney tissue, and clinical samples were increased by progression of diabetic nephropathy." (PMID 33922243, 2021). "Moreover, the increase in serum complement C4B level is also related to diabetes nephropathy." (PMID 38915894, 2024). "However, urinary C4b level was increased in diabetic nephropathy." (PMID 33922243, 2021). "The urinary levels of C4b, CFD, CXCR6, LIF, KIM-1, and NGAL were markedly increased in diabetic nephropathy patients compared to normal subjects." (PMID 33922243, 2021). "The reliability of C4b, CFD, CXCR6, and LIF as a biomarker for detecting diabetic nephropathy was investigated in clinical trials." (PMID 33922243, 2021). "Based on a preliminary scale of clinical urine tests, it was also found that C4b, CXCR6, CFD, and LIF were demonstrated to be biomarker candidates for early detection of diabetic nephropathy." (PMID 33922243, 2021). "Further, urinary C4b, CXCR6, CFD, and LIF levels might also potentially be employed as biomarkers to monitor the effectiveness of pharmacological interventions in diabetic nephropathy patients." (PMID 33922243, 2021). "The role of C4b in progression of diabetic nephropathy is not clearly elucidated." (PMID 33922243, 2021). "Thus, we selected the complementary complement 4b (C4b), complement factor D (CFD), C-X-C motif Chemokine Receptor 6 (CXCR6), and leukemia inhibitory factor (LIF) as candidate biomarkers for early detection of diabetic nephropathy." (PMID 33922243, 2021).
glaucoma (3 papers, 2017 to 2024). Increased pressure in the eyeball due to obstruction of the outflow of aqueous humor. "Upregulated C3 levels in the AH of African Americans could be one of the factors posing higher risks for glaucoma severity, with subsequent complement cascade activation triggering the proteolytic cleavage of C3 into C3a and C4b." (PMID 37763167, 2023). "Furthermore, the findings from our study indicate that four additional complement proteins, C4A, C4B, F2, and C7, were significantly elevated in the African American population with glaucoma compared to those with cataracts." (PMID 37763167, 2023). "We quantified the majority of key proteins associated with classical complement pathway, such as C1q, C1s, C1r, C4a, C4b, C3, C5, C6, C7, C8a, C8b, C8g and C9, as up-regulated in glaucoma condition for both vitreous and retinal tissues when compared to the controls." (PMID 28978942, 2017).
leprosy (3 papers, 2013 to 2020). Leprosy is a chronic infectious disease affecting primarily the skin and peripheral nervous system. "Other studies have reported associations between C4B deficiency and another mycobacterial disease, leprosy." (PMID 24638111, 2014). "In contrast, haplotypes associated with normal L-ficolin levels were protective against clinical leprosy and C4B deficiency (C4B*Q0) increases the risk to pathological immune reactivity in lepromatous disease." (PMID 23935922, 2013).
leukemia (3 papers, 2017 to 2024). A malignant (clonal) hematologic disorder, involving hematopoietic stem cells and characterized by the presence of primitive or atypical myeloid or lymphoid cells in the bone marrow and the blood. "Furthermore, our findings indicate up-regulation of genes related to complement (C4A, C4B, and SERPING1) in BM-MSC exposed to leukemia in vivo." (PMID 29137349, 2017).
periodontitis (3 papers, 2021 to 2025). An acute or chronic inflammatory process that affects the tissues that surround and support the teeth. "C4B and C4A, respectively, encode the basic and acidic forms of the complement factor 4, and C4 gene deficiency has been noted to predispose the development of severe chronic periodontitis." (PMID 33869630, 2021). "The expression of C3, C3b, and C4b was also discovered to be elevated in the gingival tissue of individuals with periodontitis, and its expression was found to be positively connected with the severity of the condition." (PMID 38218802, 2024). "Among these 48 crosstalk genes and the chronic periodontitis-related genes in DisGeNET, C4A, C4B, CXCL12, FCGR3A, IL1B, and MMP3 were shared and identified as the most pivotal candidate links between periodontitis and AD." (PMID 33869630, 2021). "Exploration of available transcriptomic datasets revealed C4A, C4B, CXCL12, FCGR3A, IL1B, and MMP3 as the top candidate molecular linkage genes between periodontitis and AD." (PMID 33869630, 2021).
psychosis (3 papers, 2022 to 2026). "We analyzed cerebrospinal fluid (CSF) levels of C4A, C4B, C1Q, along with 48 inflammation-related proteins, measured in both CSF and plasma, in 90 healthy controls and 113 patients with first-episode psychosis (FEP)." (PMID 42000733, 2026). "Our findings outline that a specific dysregulation of C4A isotype levels may exist in psychosis, at least in the very early stages of the illness, which could not be detected using methods that estimate total amount of complement C4 (i.e., C4A and C4B levels)." (PMID 35532796, 2022). "At a group level, Complement C8B, C4B, C5, and leucine-rich α-2 glycoprotein 1 (LRG1) were associated with transition to psychosis but did not surpass correction for multiple comparisons." (PMID 38243809, 2024). "C4B, Complement C4-A (C4A), Complement C2 (C2), A2M, LRG1, and the Fibrinogen alpha, beta, and gamma chains (FGA, FGB, and FGG) were differentially expressed between those who transitioned to psychosis and those who did not, adjusting for age, sex, and study." (PMID 38243809, 2024).
Stroke (3 papers, 2012 to 2019). Sudden impairment of blood flow to a part of the brain due to occlusion or rupture of an artery to the brain. "Maximum circulating concentration of complement components associated with the classical and lectin pathways of activation, C1q, C2 and C4b, and end stage mediators common to all pathways, C5 and C9, were increased in the first seven days after stroke in comparison to non-stroke controls." (PMID 31700615, 2019).